SMAD4 (SMAD family member 4)
Diseases named in the same sentence as SMAD4 in open-access papers (continued):
Sharing a sentence is not in itself a finding about the gene and the disease.
gastric cancer (continued). "The results indicated higher expression of EBV-miR-BART6-5p in gastric cancer tissues of EBVaGC patients and elevated levels in the SUN719 cell line compared to AGS and MKN45, with a relatively low expression of the target gene SMAD4." (PMID 38686046, 2024). "We examined TGF-β1, SMAD4, and TSPAN12 expression in gastric cancer tissues between the two groups." (PMID 35879950, 2022). "Finally, a positive correlation between NEAT1 and TGFβR2, VEGF-A, Smad4, PDGFB was seen in GEO gastric cancer datasets GSE62254 (n = 200)." (PMID 34552925, 2021). "Moreover, the present study identified SMAD4 as a direct target of miR-146a in SNU601 BARF1 cells, providing the first experimental evidence in stomach cancer cells." (PMID 27438138, 2016). "Although the role of SMAD4 in the prognosis of EBV-positive stomach cancer patients has not been described previously, several reports have shown that SMAD4 loss is associated with poor prognosis in advanced stomach cancer patients." (PMID 27438138, 2016). "Notably, the expression levels of Smad4 or miR-558 were inversely (R=−0.663, P<0.001) and positively (R=0.817, P<0.001) correlated with those of HPSE in gastric cancer tissues, respectively." (PMID 27685626, 2016). "The results of the present study suggest that SMAD4 may have different implication between EBV-positive stomach cancer and EBV-negative stomach cancer." (PMID 27438138, 2016). "We also reported that TOB1 overexpression in human gastric cancer (MKN28 and AGS) cells restored the levels of SMAD4 and increased the promoter activity and the mRNA and protein level of its target gene CDKN2B (P15(INK4B)), thereby inducing cell cycle arrest and apoptosis." (PMID 26694352, 2015). "Similarly, the expression of SMAD4 was lower, whereas SMAD7 was found to positively correlate with tumor grading in human glioma and gastric cancer." (PMID 25295107, 2014). "However, its downregulation led to the promotion of proliferation, colony formation, EMT, and migration of gastric cancer cells (BGC-823 and SGC-7901), along with increased TGF-β signaling pathway-related proteins, including TGF-β, phospho-Smad2, Smad2, Smad3, and Smad4." (PMID 39768197, 2024). "In addition, we found that SMAD4 was low-expressed in gastric cancer tissues and high-expressed in the corresponding adjacent normal tissues and GLUT1 and HK2, key proteins for glycolysis, are relatively more highly expressed in gastric cancer tissues." (PMID 38686046, 2024). "Thus, the induction of Smad4 expression by Tob1 in MKN28 and AGS cells could inhibit gastric cancer progression through activation of Smad4-mediated signaling." (PMID 22710759, 2012). "A negative correlation between Smad4 and HPSE immunoreactivity was noted in gastric cancer cases (correlation coefficient R=−0.614, P<0.001)." (PMID 27685626, 2016). "Notably, mining the publicly available Gene Expression Omnibus (GEO) datasets indicated the negative correlation between Smad4 and HPSE levels in different gastric cancer cohorts." (PMID 27685626, 2016). "Additionally, there is also research that hsa_circ_0004872 can inhibit ADAR1 expression through hsa_circ_0004872/miR-224/Smad4/ADAR1 negative feedback loop and exert oncogenic effects in gastric cancer (GC)." (PMID 38233935, 2024).
pancreatic ductal adenocarcinoma (81 papers, 2007 to 2026). An infiltrating adenocarcinoma that arises from the epithelial cells of the pancreas. "SMAD4 inactivation is a paradigm of such mutations and a hallmark of pancreatic ductal adenocarcinoma (PDAC)." (PMID 40999053, 2025). "In pancreatic ductal adenocarcinoma, loss of SMAD4 induces the upregulation and nuclear translocation of the glycolytic enzyme PGK1, resulting in high oxidative phosphorylation and metastatic potential." (PMID 40139191, 2025). "Dysregulation of SMAD4 (i.e. somatic mutation) is strongly associated with poor pancreatic ductal adenocarcinoma (PDAC) prognosis, yet the molecular mechanisms remain underlying this relationship obscure." (PMID 39528473, 2024). "Downregulation of SMAD4 was associated with the metastasis of pancreatic ductal adenocarcinoma (PDAC), and metastasis of SMAD4-negative PDAC was preferentially derived from the induction of mitochondrial OXPHOS." (PMID 39593114, 2024). "Smad4, a key mediator of the transforming growth factor‐β signaling, is mutated or deleted in 20% of pancreatic ductal adenocarcinoma (PDAC) cancers and significantly affects cancer development." (PMID 35064757, 2022). "SMAD4 is frequently inactivated and associated with a poor prognosis in pancreatic ductal adenocarcinoma (PDAC)." (PMID 31684910, 2019). "SMAD4 inactivation by allelic deletion or intragenic mutation mainly occurs in the late stage of human pancreatic ductal adenocarcinoma (PDAC)." (PMID 24625091, 2014). "Activating K-Ras mutations and inactivating mutations of Smad4 are two common genetic alterations that occur in the development and progression of pancreatic ductal adenocarcinomas (PDAC)." (PMID 24340014, 2013). "SMAD4/DPC4 mutations have been associated with aggressive behavior in pancreatic ductal adenocarcinomas (PDAC), and it has recently been suggested that RUNX3 expression combined with SMAD4 status may predict the metastatic potential of PDACs." (PMID 29100342, 2017). "The loss of SMAD4, which as been reported to occur in 55% of pancreatic ductal adenocarcinomas may lead to up regulation of cell cycle proteins and hence increase cellular proliferation." (PMID 17587453, 2007). "Thus, the loss of SMAD4 expression in pancreatic ductal adenocarcinoma leads to upregulation of cell cycle proteins and hence increases cellular proliferation." (PMID 17587453, 2007). "Using pancreatic ductal adenocarcinoma as a model system, we performed a SMAD4-focused oncogenic protein–protein interaction mapping and uncovered a novel interaction between SMAD4 and NFATc1." (PMID 40856537, 2026). "In pancreatic ductal adenocarcinoma (PDAC), SMAD4 mutations are particularly prevalent, occurring in ∼50% of cases, and are strongly associated with shorter survival and poor prognosis." (PMID 40856537, 2026). "A recent study similarly reported that PRDM16 acts as a SMAD4 co-repressor during pancreatic ductal adenocarcinoma progression." (PMID 40658097, 2025). "In SMAD4‐positive pancreatic ductal adenocarcinoma (PDAC), integrin subunit alpha V (ITGAV) activates latent TGF‐β, which binds to the TGF‐β receptor and phosphorylates SMAD2/3." (PMID 40739706, 2025).
pancreatic ductal adenocarcinoma (continued). "To investigate the clinical implications of the SMAD4 status on radiotherapy resistance, we conducted IHC analyses of SMAD4 in tissue microarrays from 86 pancreatic ductal adenocarcinoma (PDAC) patients, comparing tumor tissues with adjacent normal tissues." (PMID 39528473, 2024). "One study showed that KLF5 inhibition in SMAD4-mutant pancreatic ductal adenocarcinoma cells is accompanied by increased apoptosis." (PMID 37377893, 2023). "sEVs originated from pancreatic ductal adenocarcinoma cells with the missing SMAD4 contribute to the MDSCs proliferation via increased glycolysis and calcium flux by means of transporting differentially expressed miRNA and protein relevant to SMAD4." (PMID 37208722, 2023). "It has been shown that SMAD4-deleted pancreatic ductal adenocarcinoma cells are sensitive to agents modulating the cell cycle." (PMID 34880877, 2021). "We examined TGF-βR2 and SMAD4 protein expression in biopsy or surgical samples from 91 patients with pancreatic ductal adenocarcinoma (PDAC) using immunohistochemistry." (PMID 24465802, 2014). "Smad4 knock-out accelerates the development of pancreatic ductal carcinomas and metastases in the context of K-RasG12D transgenic mice." (PMID 22614218, 2012). "Our observations further adds to preexisting data and establish Smad4 as a potential prognostic marker for pancreatic ductal adenocarcinoma." (PMID 22195733, 2011). "In this work, we further establish the role of Smad4 as a potential prognostic marker for pancreatic ductal adenocarcinoma." (PMID 22195733, 2011). "In the present study, we examined the differential protein expressions of Smad4, Smad6 and Smad7 in surgically resected samples of paired tumor tissue of pancreatic ductal adenocarcinoma versus adjacent normal tissue." (PMID 22195733, 2011). "Despite one report of Smad4 expression to be inversely related to survival in surgically resected pancreatic ductal adenocarcinoma patients, there is growing evidence for the correlation of Smad4 status to patient survival in this disease." (PMID 22195733, 2011). "This study investigates the differential protein expressions of Smad4, Smad6 and Smad7 in tumor as compared to normal tissue of pancreatic ductal adenocarcinoma (PDAC) and compares them with clinicopathological parameters and patient survival." (PMID 22195733, 2011). "Protein levels of all three Smads, Smad4, Smad6 and Smad7 were evaluated in paired normal pancreatic tissues and tumor samples of pancreatic ductal adenocarcinoma." (PMID 22195733, 2011).
pancreatic ductal adenocarcinoma (continued). "In view of these results the sensitivity for SMAD4 for pancreatic ductal adenocarcinoma is 80% while for CA19-9 and CK19 it is 100%." (PMID 17587453, 2007). "In primary pancreatic ductal adenocarcinoma, CK 19 showed diffuse cytoplasmic positivity in 23 of 25 cases, CA 19-9 showed apical cytoplasmic staining in all 25 cases, and SMAD4 showed nuclear staining in 20 of 25 cases." (PMID 17587453, 2007). "Moreover, AGR2 expression is suppressed by SMAD4 that is a tumor suppressor of pancreatic ductal adenocarcinoma." (PMID 25367337, 2014). "For instance, human pancreatic ductal adenocarcinoma (PDAC) is characterized besides the common K-Ras mutations (representing an early event in PDAC tumourigenesis) by both TGF-βoverexpression and mutational inactivation of the tumour suppressor Smad4/DPC4, the latter being a relatively late event." (PMID 21624123, 2011). "Pancreatic ductal adenocarcinoma (PDAC) is characterized by frequent SMAD4 inactivation and profound lipid metabolic rewiring, yet how these processes intersect especially in SMAD4+ PDAC remains elusive." (PMID 41885390, 2026). "For example, SMAD4 inhibits tumor progression initiated by KRAS (G12D) in pancreatic ductal adenocarcinomas (PDAC); in a subset of advanced tumor, intact SMAD4 promotes TGF‐β‐dependent growth and EMT." (PMID 39957375, 2025). "In summary, our study shows that SMAD4, CK19 and CA19-9 are helpful markers for confirming the diagnosis of primary pancreatic ductal carcinoma." (PMID 17587453, 2007). "Thus, in pancreatic ductal adenocarcinoma cases where Smad4 itself is not lost, we illustrate a novel mechanism for its inhibition." (PMID 22195733, 2011).
prostate carcinoma (76 papers, 2010 to 2025). A carcinoma that arises from epithelial cells of the prostate gland. "PTEN inactivation also induces TGF-β/BMP signaling, and knockout of Smad4 overcomes senescence caused by Pten deletion and results in invasive, metastatic, and lethal prostate cancers with 100% penetrance." (PMID 38781024, 2024). "In prostate cancer cell lines and PTEN-null mouse model of prostate cancer, SMAD4 loss has been shown to promote invasion and metastasis." (PMID 36175474, 2022). "Apc loss has also been shown to cooperate with hepsin overexpression or Smad4 loss to promote invasive prostate cancer, further indicating that invasive progression in Apc-deficient prostate cancer requires an additional genetic alteration." (PMID 35204808, 2022). "Following the evidence that AR interacts with SMAD proteins in prostate cancer, we proposed that SMAD4 dynamically associates with AR to orchestrate specific gene expression programmes in a time- and context-dependent fashion." (PMID 35522298, 2022). "In this mechanism, PTEN loss and SMAD4 inactivation or inhibition through either genetic deletion of SMAD4 leads to tumor progression in a mouse model of prostatic cancer." (PMID 34638474, 2021). "Genistein treatment in prostate cancer significantly down-regulated miR-1260b and caused subsequent up-regulation of its targets sFRP1 and Smad4 by DNA demethylation and histone modifications, which caused a suppression of prostate cancer cells." (PMID 34289845, 2021). "Of note was PI3K family members: PIK3C2G, PIK3CA, PIK3CB, PIK3R4, Mucin family members: MUC1, MUC4 and MUC6 and other prostate cancer associated genes such as SMAD4, SOX9 and SPOP7,9,40,41." (PMID 32796921, 2020). "We attempted to prove that ETV1 overexpression cooperates with SMAD4 loss in the development of prostate cancer by emulating such a situation with our ETV1;Pb-Cre4;Smad4f/f compound mice." (PMID 31160676, 2019). "Loss of Smad4 has also been found in human prostate cancer and drives tumorigenesis and metastasis when coupled with other genetic aberrations in mouse models." (PMID 29113300, 2017). "We show here that loss of both Apc and Smad4 results in invasive, castration-resistant prostate carcinoma with androgen receptor (AR) loss." (PMID 29113300, 2017). "For example, downregulation or loss of the SMAD4 gene is associated with an aggressive phenotype of prostate cancer." (PMID 28005952, 2016). "In advanced prostate cancer, the TGFβ/Smad4 signaling pathway is activated upon the loss of PTEN expression." (PMID 25295225, 2014). "Moreover, interruption of Klf5 acetylation promoted tumor growth, accelerated cell proliferation, enhanced the formation of tumor organoids, and altered Smad4-knockout–associated genes in Pten-deficient prostate cancer." (PMID 38781024, 2024). "Thus, although mutations in SMAD4 are rare events in prostate cancer and HCC, methylation of its promotor is commonly detected and associated with reduced expression." (PMID 34571856, 2021). "Similarly, the loss of Smad4 promotes cancer cell growth and metastatic progression in both colorectal and prostate cancer." (PMID 31349837, 2019). "Loss of miR-15 and miR-16 in prostate cancer cells potentiates TGF-β signaling by upregulating USP9X (a gene encoding an enzyme deubiquitinating SMAD4), as well as activin RIIA, an activin receptor, contributing to the survival of cancer cells in bone marrow and the formation of bone metastasis." (PMID 31842336, 2019). "The Wnt pathway and Smad4 have been linked in prostate cancer." (PMID 29113300, 2017).